FKBP5 (FKBP prolyl isomerase 5)
Diseases named in the same sentence as FKBP5 in open-access papers (continued):
Sharing a sentence is not in itself a finding about the gene and the disease.
preeclampsia (2 papers, 2021 to 2025). Preeclampsia is a hypertensive disorder of pregnancy that is characterized by new-onset hypertension with proteinuria presenting after 20 weeks of gestation, and depending on mild or severe forms may initially present with severe headache, visual disturbances, and hyperreflexia. "Interestingly, this module significantly overlaps with genes that have previously been associated with preeclampsia, with genes upregulated in preeclampsia also showing positive correlation with FKBP5 expression." (PMID 34446099, 2021). "RT‒qPCR analysis confirmed the upregulation of FKBP5, LAMA5, FZD5 and FGG mRNA expression in preeclampsia." (PMID 40490753, 2025).
Rett syndrome (2 papers, 2008 to 2023). A severe neurodevelopmental disorder affecting the central nervous system. "Fkbp5 has already been identified as an upregulated gene in the mouse model of Rett Syndrome so can be considered as a positive control of the accuracy and appropriateness of the experiments." (PMID 18989361, 2008).
alcohol withdrawal syndrome (1 paper, 2023). "FKBP5 variants modulate the severity of alcohol withdrawal syndrome, and predict the propensity of heavy drinking in humans." (PMID 36792579, 2023).
anaemia (1 paper, 2024). "The lower PCV (anaemia) and TPP values, and elevated expression of a stress receptor pathway gene FKBP5, occurring in time point B, are all consistent with expected impacts of extreme ambient temperatures." (PMID 38538683, 2024).
atrial fibrillation (1 paper, 2023). A disorder characterized by an electrocardiographic finding of a supraventricular arrhythmia characterized by the replacement of consistent P waves by rapid oscillations or fibrillatory waves that vary in size, shape and timing and are accompanied by an irregular ventricular response. "Indeed, the loss of function of the FKBP5 gene has a significant impact on atrial fibrillation development and cardiac function." (PMID 37398599, 2023).
attention deficit-hyperactivity disorder (1 paper, 2024). A disorder characterized by a marked pattern of inattention and/or hyperactivity-impulsivity that is inconsistent with developmental level and clearly interferes with functioning in at least two settings (e.g. at home and at school). "In addition, FKBP5 was associated with MDD, bipolar disorder, schizophrenia, posttraumatic stress disorder, attention deficit hyperactivity disorder (ADHD), chronic pain and metabolic dysfunction, insulin resistance and obesity." (PMID 37581323, 2024).
autism (1 paper, 2025). Persistent deficits in social interaction and communication and interaction as well as a markedly restricted repertoire of activity and interest as well as repetitive patterns of behavior.
B cell lymphoma (1 paper, 2012). "In this study, we knocked out FKBP5 and RCAN1 alleles independently in a human pre-B cell lymphoma cell line, Nalm-6, by gene targeting." (PMID 23185487, 2012).
Behcet disease (1 paper, 2020). A chronic, relapsing, multisystemic vasculitis characterized by mucocutaneous lesions, as well as articular, vascular, ocular and central nervous system manifestations. "Interestingly, in a recent study on the Behcet’s disease (BD) hypomethylation in the 5′UTR region (including cg03546163) of FKBP5 characterized cases was demonstrated and it was strongly associated with high gene expression, suggesting a possible role of DNA methylation in the pathogenesis." (PMID 33233407, 2020).
benign prostatic hyperplasia (1 paper, 2021). A non-cancerous nodular enlargement of the prostate gland. "Furthermore, differential quantitative proteomic analysis of patients with PCa and benign prostatic hyperplasia (BPH) showed a significant decrease in FKBP5, FAM129A, RAB27A, FASN, NEFH proteins after local PCa treatment." (PMID 33810357, 2021).
bovine tuberculosis (1 paper, 2024). "In an earlier cattle QTL mapping study, the most significant associations with bovine tuberculosis were located on the FKBP5 gene." (PMID 39795948, 2024).
cerebral infarction (1 paper, 2020). An ischemic condition of the brain, producing a persistent focal neurological deficit in the area of distribution of the cerebral arteries. "A higher expression of FKBP5 was tested in the plasma from patients who suffered larger cerebral infarction." (PMID 32760250, 2020).
Cirrhosis (1 paper, 2022). A chronic disorder of the liver in which liver tissue becomes scarred and is partially replaced by regenerative nodules and fibrotic tissue resulting in loss of liver function. "We could observe that the A1 subtype-related markers (FKBP5, GBP2, PSMB8, and SRGN) were remarkably elevated in HE samples compared to healthy control samples and cirrhosis samples." (PMID 36424620, 2022).
cognitive decline (1 paper, 2025). "If studies confirm a synergistic effect between ELA and genetic factors like APOE ɛ4 or FKBP5 on inflammation and cognitive decline, it could lead to targeted screening programs for individuals with both ELA history and genetic risk factors." (PMID 40001464, 2025).
Crohn disease (1 paper, 2015). A gastrointestinal disorder characterized by chronic inflammation involving all layers of the intestinal wall, noncaseating granulomas affecting the intestinal wall and regional lymph nodes, and transmural fibrosis. "Furthermore, RA is considered to be a polygenic disease, and other polymorphisms are likely to be related to disease activity and/or response to GC treatment as has been shown for instance for FKBP5 in Crohn’s disease." (PMID 25724472, 2015).
cytomegalovirus infection (1 paper, 2021). A herpesvirus infection caused by Cytomegalovirus. "Other similar GE interplay are those of FK Binding Protein Prolyl Isomerase 5 (FKBP5) and childhood trauma, AKT-8 retrovirus Serine/Threonine Kinase 1 (AKT1) and cannabis use, and Catenin Alpha 3 (CTNNA3) and cytomegalovirus infection in utero." (PMID 34829493, 2021).
delirium (1 paper, 2022). A disorder characterized by confusion; inattentiveness; disorientation; illusions; hallucinations; agitation; and in some instances autonomic nervous system overactivity. "In a population of postoperative older adults, delirium status was associated with three SNPs: KIBRA SNP rs17070145, MTNR1B SNP rs10830963, and FKBP5 SNP rs1360780." (PMID 35017578, 2022). "Our results highlight the relevance of KIBRA, MTNR1B, and FKBP5 in understanding the complex relationship between delirium, cognition, and sleep, which warrant further study in larger, more diverse populations." (PMID 35017578, 2022). "Interestingly, individuals without delirium may also have increased odds of FKBP5 SNP rs1360780 CT/TT, which is associated with worse cognition in aging and after stress." (PMID 35017578, 2022). "FKBP5 SNP rs1360780 CT/TT (vs. CC) demonstrated borderline increased adjusted odds of not developing delirium (aOR 2.51, 95% CI 1.00, 7.34; p = 0.05)." (PMID 35017578, 2022). "Subjects without delirium had borderline higher odds of having FKBP5 SNP rs1360780 CT/TT (vs. CC) in adjusted models (aOR 2.51, 95% CI 1.00, 7.34; p = 0.05)." (PMID 35017578, 2022).
demyelinating disease (1 paper, 2023). A broad group of disorders that affect the myelin sheaths that cover the neurons. "However, few studies have focused on mitophagy regulation of FKBP5 in demyelinating diseases." (PMID 37952053, 2023). "Therefore, we used FKBP5-PPAR-γ-Bcl2 as the core and spread outward to search for possible key nodes between CNS demyelinating diseases and mitophagy, and tested the expected accuracy by subsequent experiments." (PMID 37952053, 2023). "This study reveals the role of FKBP5 in regulating a dynamic pathway of natural restorative regulation of mitophagy through PPAR-γ in pathological demyelinating settings, which may provide potential targets for the treatment of demyelinating diseases." (PMID 37952053, 2023).
dilated cardiomyopathy (1 paper, 2024). Cardiomyopathy which is characterized by dilation and contractile dysfunction of the left and right ventricles. "FKBP5 (FKBP Prolyl Isomerase 5, 602623) was shown to be down-regulated in dilated cardiomyopathy, as reported by previous transcriptomic and methylation studies." (PMID 39202774, 2024). "As for the cardiomyocytes, FKBP5 (FKBP Prolyl Isomerase 5, 602623) had previously been reported to be down-regulated in dilated cardiomyopathy." (PMID 39202774, 2024).
E. coli infection (1 paper, 2013). "FKBP5 is highly expressed in murine T cells and therefore the up-regulation observed during E. coli infection may be due to lymphocyte migration into mammary gland tissue." (PMID 23324411, 2013).
emotional dysregulation (1 paper, 2018). "Thus, we examined three FKBP5 single nucleotide polymorphisms (SNPs) commonly implicated in stress-related emotional dysregulation." (PMID 29867390, 2018). "Relevant to the present report, FKBP5 is implicated in emotional dysregulation." (PMID 29867390, 2018). "The limitations of the present project constrain the generality of the results, but they are encouraging in supporting a growing literature linking FKBP5 expression and exposure to stressors (e.g., childhood trauma) to emotional dysregulation." (PMID 29867390, 2018).
endometrial adenocarcinoma (1 paper, 2025). "Our previous research indicated that reduced FKBP5 levels in endometrial adenocarcinoma tissues promote cancer cell proliferation by increasing p-AKT levels while simultaneously decreasing the sensitivity of these cancer cells to progesterone therapy." (PMID 41271936, 2025).
fibromyalgia (1 paper, 2014). A chronic disorder of unknown etiology characterized by pain, stiffness, and tenderness in the muscles of neck, shoulders, back, hips, arms, and legs. "Fibromyalgia has been genetically linked to the HLA region (6p21.3) 63, which includes several genes associated with Notch signalling (e.g. Notch4, FKBP5, TNXB, MTCH1 and TNF-a) or with stem cell maintenance and proliferation (e.g. POU5F1, Flot1, MAPK14, Rgl2 and Rab44)." (PMID 25164209, 2014).
glioblastoma (1 paper, 2017). The most malignant astrocytic tumor (WHO grade IV). "FKBP5 encodes a large immunophilin which was originally cloned in lymphocytes but also found abundantly expressed in several tumours, including glioblastoma." (PMID 28978117, 2017).
head and neck squamous cell carcinoma (1 paper, 2023). A squamous cell carcinoma that arises from any of the following anatomic sites: lip and oral cavity, nasal cavity, paranasal sinuses, pharynx, larynx, and salivary glands. "Analysis of the GEPIA database also demonstrated that the expression of the FKBP5 gene was obviously upregulated in 519 HNSC (head and neck squamous cell carcinoma) tissues compared with that in 44 normal tissues." (PMID 36769373, 2023).
heart failure (1 paper, 2023). Inability of the heart to pump blood at an adequate rate to meet tissue metabolic requirements. "The FKBP5 gene product is a potential biomarker and therapeutic agent for heart failure and may be used to diagnose heart failure with an LVAD." (PMID 37008310, 2023).
hyperandrogenism (1 paper, 2022). Excessive secretion of androgens from the adrenal glands or gonads. "We detected differences between the hyperandrogenism and non-hyperandrogenism PCOS subtype groups for five SNP alleles of the FKBP5 gene." (PMID 35787810, 2022). "Our study showed that FKBP5 gene polymorphisms are associated with PCOS generally (rs1360780 and rs3800373) and with the hyperandrogenism subtype specifically (rs1360780, rs9470080, rs9296158, rs1043805 and rs7757037)." (PMID 35787810, 2022). "Our study showed that the FKBP5 gene is a potential association gene for PCOS, with some SNP genotypes associated with PCOS generally and with the hyperandrogenism subtype specifically." (PMID 35787810, 2022). "The present study aimed to determine whether polymorphisms in the FK-506 binding protein 5 (FKBP5) gene (androgen target gene) are associated with an association for PCOS and hyperandrogenism." (PMID 35787810, 2022). "In this study, we evaluated potential genetic influences of 13 SNPs of androgen-responsive gene FKBP5 in Han Chinese women with PCOS, with a particular focus on the hyperandrogenism PCOS subtype." (PMID 35787810, 2022).
Hyperinsulinemia (1 paper, 2022). An increased concentration of insulin in the blood. "Because eplerenone decreased the Fkbp5 induction and hyperinsulinemia caused by dexamethasone alone, our data also suggest that dexamethasone at the given dose can act through MR, which is also in line with previous observations." (PMID 36034417, 2022).
infarction (1 paper, 2025). A localised pathological necrosis of tissue resulting from obstruction of the blood supply usually by a thrombus, an embolus, or vascular torsion. "In our study, we observed increased Fkbp5 levels in OGD/R-treated astrocytes and peri-infarction tissue of the HT model, which were reduced by miR-29a-5p overexpression." (PMID 40529227, 2025).
lipoma (1 paper, 2024). A benign, usually painless, well-circumscribed lipomatous tumor composed of adipose tissue. "To assess the impact of FKBP5 on adipogenesis in vivo, we established a lipoma model in female nonobese diabetic/severe combined immunodeficiency mice by co-implanting FAPs in Matrigel." (PMID 39020442, 2024).
liver cancer (1 paper, 2022). An epithelial or non-epithelial malignant neoplasm that arises from the liver. "In the analysis of immune cells and immune factors, FKBP5 specifically and negatively correlated with a variety of immune effector cells and immune effector factors in the microenvironment of liver cancer." (PMID 35865544, 2022). "In liver cancer, FKBP5 was related to tissue type and immune infiltration, but not to the degree of fibrosis." (PMID 35865544, 2022).
lupus nephritis (1 paper, 2024). Glomerulonephritis in the context of systemic lupus erythematosus. "In the comparison of 62 subgroups, the up-regulated gene (PTPRC, MX1) and the down-regulated DEGs (EGR1, MME, RORC, ZBTB16, FKBP5) were verified to have mostly consistent change trends in all Lupus Nephritis vs. Normal Kidneys group with the results of GSE200306." (PMID 39301055, 2024).
myelofibrosis (1 paper, 2017). A partial or complete replacement of the bone marrow stroma by fibrous tissue. "FKBP5 is known to be related with myelofibrosis, another type of fibrotic disease in which the bone marrow is replaced by fibrotic tissue." (PMID 28974751, 2017).
neuroblastoma (1 paper, 2023). Neuroblastoma (NB) is the most common solid, extracranial childhood tumor. "Armadillo repeat containing 12 (ARMC12) is located 3 kb upstream of FKBP5 and has been reported to promote neuroblastoma progression and play crucial roles in spermiogenesis." (PMID 37274192, 2023).
osteosarcoma (1 paper, 2023). A usually aggressive malignant bone-forming mesenchymal neoplasm, predominantly affecting adolescents and young adults. "B/My MPAL blast cells from induction failure patients showed high expression of MT2A and FKBP5 genes that are associated with chemoresistance in osteosarcoma, solid cancers, and ALL." (PMID 37845689, 2023).
phobias (1 paper, 2023). "In humans, decreased levels of FKBP5 methylation detected in blood samples was found to be associated with better cognitive behavioral therapy (CBT) treatment outcomes from pretreatment to post-treatment patients formally diagnosed with phobias." (PMID 35998298, 2023).
pituitary gland adenoma (1 paper, 2021). A non-metastasizing tumor that arises from the adenohypophysial cells of the anterior lobe of the pituitary gland. "In AtT20, a pituitary gland adenoma cell line elevating or reducing Crabp1 level correspondingly increases or decreases FKBP5 expression, and its endogenous Crabp1 level is elevated by GR agonist dexamethasone or RA treatment." (PMID 34830120, 2021).
prion disease (1 paper, 2020). A transmissible disease that is caused by a protein that is able to induce abnormal folding of normal cellular proteins, leading to characteristic spongiform brain changes, which are associated with neuronal loss without an inflammatory response. "Work from the Soto group showed that FK506, a calcineurin (CaN) inhibitor which binds to FKBP5, substantially decreased the severity of clinical signs in mice presenting symptoms of prion disease." (PMID 32918118, 2020). "Several lines of evidence support the implication of FKBP5 in prion diseases." (PMID 32918118, 2020).
prostate adenocarcinoma (1 paper, 2023). "SEMA3C expression is correlated with expression of steroidogenic enzymes CYP11A1 and SRD5A2 as well as the AR target gene, FKBP5, in prostate adenocarcinoma patients according to TCGA PanCancer dataset available on cBioPortal." (PMID 37800655, 2023).
psoriasis (1 paper, 2024). An autoimmune condition characterized by red, well-delineated plaques with silvery scales that are usually on the extensor surfaces and scalp. "On the contrary, in psoriasis, more inflammation-related spatially variable genes (e.g. SERPINF1, FKBP5, IFIT1/3, DDX58) were identified." (PMID 38433843, 2024).
retinal degeneration (1 paper, 2023). Degeneration of the retina. "Tubby-like protein 1 (TULP1) is located approximately 60 kb downstream from FKBP5 and has been reported to be important for vesicular trafficking of photoreceptor proteins and associated with early-onset retinal degeneration." (PMID 37274192, 2023).
retinal vein occlusion (1 paper, 2022). An occlusion of the retinal vein. "Our results strongly suggest that FKBP5 and CADM3 are corticosteroid-sensitive proteins in retinal vein occlusion, as the regulation of the proteins has been identified in two individual proteome studies of the DEX implant." (PMID 36080454, 2022). "We previously identified an upregulation of FKBP5 and a downregulation of CADM3 in a proteome study where the DEX implant intervention was studied in a model of experimental branch retinal vein occlusion (BRVO), a subtype in which a sector of the retina is affected by retinal vein occlusion." (PMID 36080454, 2022).
Salmonella Infections (1 paper, 2023). Infections with bacteria of the genus SALMONELLA. "Among the multiple genes detected in this study, EXFABP, S100A9/12, CEMIP, FKBP5, MAVS, FAM168B, HESX1, EMC6, and others were found as potential candidate gene and transcript (co-) factors for resistance to Salmonella infection." (PMID 36902251, 2023).
serous ovarian cancer (1 paper, 2025). "Notably, the present study revealed substantial upregulation of FKBP5 in residual high-grade serous ovarian cancer (HGSOC) tissues from patients undergoing neoadjuvant chemotherapy." (PMID 40771481, 2025).
sleep breathing disorders (1 paper, 2023). "FKBP5 variants potentially contribute to sleep breathing disorders." (PMID 37274192, 2023).
sporadic CJD (1 paper, 2023). "Although additional functional work is needed to clarify the relationship between sporadic CJD, FKBP5, and the hypothalamic pituitary adrenal (HPA) axis (where FKBP5 plays a major role), it could be that the HPA axis provides a link between the pathology in the brain and the periphery." (PMID 35307791, 2023).
thyroid cancer (1 paper, 2024). "Cell experiments demonstrated that high expression of FKBP5 promotes proliferation and inhibits apoptosis of thyroid cancer cells (thyroid cancer cells:TPC-1 and KTC-1 cell lines)." (PMID 39135992, 2024). "Immunohistochemistry results show abnormal expression of proteins such as FKBP5, CENPF, CX26, KIF11, PTK7, which are associated with poor prognosis in thyroid cancers with intraglandular dissemination, offering potential guidance for specific targeted therapy in the future." (PMID 39135992, 2024).